TNF (tumor necrosis factor)
Diseases named in the same sentence as TNF in open-access papers (continued):
Sharing a sentence is not in itself a finding about the gene and the disease.
breast carcinoma (continued). "We demonstrate that circulating neutrophils from breast cancer patients have significantly increased anticancer cell cytotoxicity and that this activity can be stimulated by the cytokine TNF (TNFα)." (PMID 28721376, 2016). "Treatment with TGF-β, EGF, and TNF-α after IL-1β further increased IL-6 expression in MCF7_TG2 breast cancer cells." (PMID 27609180, 2016). "TNF-α expression and its action have also been reported in esophageal cancer, ovarian cancer, breast cancer, and follicular thyroid cancer as well." (PMID 26881177, 2016). "Here, we tested the ability of RCE-treated breast cancer cells to migrate through TNF-α stimulated HUVECs." (PMID 26888313, 2016). "There are a number of reports showing the pro-tumourigenic effects of TNF alpha in breast cancer [reviewed in 41]." (PMID 27765923, 2016). "Then, through Spearman's rank correlation, we showed that high expression of NF-κB modulates positively the IL-6 and TNF-α expression levels in mammary tumors." (PMID 26989335, 2016). "TNFα promotes breast cancer cell proliferation and migration in vitro and contributes to mammary tumorigenesis in vivo." (PMID 25762639, 2015). "Further, the functioning of TGF-β axis in bones can be suppressed by proinflammatory cytokines as IL-1β and TNF-α, commonly found in breast cancer." (PMID 26635447, 2015). "We performed 123I-mIBG scintigraphy, conventional and strain echocardiography and biomarker (NT-proBNP, TNF-α, galectin-3, IL-6, troponin I, ST-2 and sFlt-1) assessment in 59 breast cancer survivors 1 year after anthracycline treatment." (PMID 26400150, 2015). "Here we combine quantitative mass spectrometry with random forest bioinformatics to dissect the TNF-α-IKKβ-induced phosphoproteome in MCF-7 breast cancer cells." (PMID 25849741, 2015). "In the early stages, when breast cancer is localized, patients display reduced TNF-α and IL-12 in serum, and concomitantly there are few reports of pain." (PMID 26635447, 2015). "In this way, our global phosphopeptide analysis covered a variety of TNF-α- and IKKβ-mediated phosphorylation as well as the majority of all known TNF-α pathway member events in MCF-7 breast cancer cells." (PMID 25849741, 2015). "For example, breast cancer patients often present with increased levels of circulating TNFα and IL-6, suggesting a heightened inflammatory state that correlates with hastened metastatic progression and death." (PMID 26177198, 2015). "The induction of enhanced MMP-9 expression is also essential for TNF-α-stimulated invasion of triple-negative MDA-MB-231 breast cancer cells." (PMID 26516917, 2015). "Exposure of breast cancer cells to 1 μM of DHTS for 3 h significantly reduced total TNF mRNA levels to ≈40% (P < 0.05) of the control levels." (PMID 26553968, 2015). "In a pilot study of 16 breast cancer patients, TNF-α production by peripheral blood T cells was correlated with the detection of circulating tumor cells expressing EMT markers." (PMID 26207636, 2015). "It has been demonstrated that Snail enhances TNFα-induced cancer cell migration and invasion in breast cancer cells, through stabilization of NF-κB activation." (PMID 25762639, 2015). "There were significant baseline differences between lymphoma versus breast cancer patients for TNF-α, TNFR1, TNFR2 and IL-18." (PMID 25909710, 2015). "Breast cancer cells can also produce IL-1, TNF and prostaglandins which increase RANKL expression and stimulate osteoclasts." (PMID 25923354, 2015). "Future work defining the regulation of TNF signaling during breast cancer progression will be important to target useful therapeutic interventions against this pathway." (PMID 25807548, 2015). "On the other hand, the secretion of IL-6, IL-1β and TNF was significantly lower in breast cancer patients." (PMID 25992611, 2015).
breast carcinoma (continued). "In the present study, both fibroblast- and breast cancer-CM showed similar effects on macrophages, as both induced higher secretion levels of TNF-α and higher MMP-9 activity in LPS stimulated macrophages." (PMID 25588705, 2015). "We checked that AS602868 effectively targeted canonical NF-kB pathway in breast cancer cells by evaluating its capacity to counteract TNFα-induced activation of NF-kB transcription using a NF-kB gene reporter assay and to potentiate TNFα-induced cell death." (PMID 25974963, 2015). "NF-κB signaling was recently reported to trigger the progression of TNF-α-induced EMT in breast cancer by activating Twist." (PMID 26176983, 2015). "This molecular mechanism of action has a therapeutic relevance, as shown by the inhibitory effect on viability, proliferation and chemotaxis of breast cancer cell lines and by the decreased TNF production in macrophages cells." (PMID 26553968, 2015). "Surprisingly, C57BL/6 BMDMs cultured with 4T1 mouse mammary carcinoma-conditioned medium exhibited a 2–3 fold increase in the production of TNFα, IL-6, and CCL2 in the presence of LPS." (PMID 26177198, 2015). "Considering the results presented in this study, depletion of Her-2-specific IL-5- and IL-17-producing CD4+ T-cells and enrichment of TNF-producing CD8+ T-cells for adoptive T-cell therapy would be important in breast cancer." (PMID 26500775, 2015). "The activities of CAFs and MSCs in breast cancer are integrated within an intimate inflammatory tumor microenvironment (TME) that includes high levels of tumor necrosis factor α (TNF-α) and interleukin 1β (IL-1β)." (PMID 25928089, 2015). "This is further established in mouse models of breast cancer in which ablation of TNFα or IL-6 results in reduced metastasis." (PMID 26177198, 2015). "In comparing with CTGF, TNFR1 has been extensively studied to mediate the function of TNF-α in promoting breast cancer growth, and blockage of TNFR1 with specific antibodies was enough to impair TNF-α signaling and biological effects." (PMID 26318291, 2015). "We recently reported that TNF-α and IL-1β were minimally expressed by normal breast epithelial cells, but were highly expressed in tumor cells of biopsies from most breast cancer patients." (PMID 25928089, 2015). "Accordingly, inhibition of TNF-α or its receptors has prominent anti-tumor effects in animal models of breast cancer." (PMID 25928089, 2015). "In the current study, following TNF-α treatment in breast cancer MCF-7 cells, the expression of TRAF4 suppressed the activation of NF-κB and promoted early cell apoptosis." (PMID 24396457, 2014). "The activation of WT-Ras by TNFα stimulation demonstrates that inflammatory factors can activate oncogenic pathways in breast tumor cells and promote disease progression in breast cancer." (PMID 24598028, 2014). "Circulating levels of the inflammatory cytokines IL-6 and TNF-α have also been used as evidence of aberrant HPA axis regulation in breast cancer patients and other populations." (PMID 24731917, 2014). "This study aimed to investigate the effects of TNF-α in combination with WA or Cel in vitro in MDA-MB-231 breast cancer cells." (PMID 25419573, 2014). "A complex variety of cytokines and growth factors such as TGF-β, hepatocyte growth factor (HGF), epidermal growth factor (EGF), and tumour necrosis factor α (TNFα) have been shown to influence MMP 9 induction by fibroblasts in breast cancer cells." (PMID 24800085, 2014). "Nevertheless, the actual evidence for such TNFα activity significantly contributes to our understanding of the interactions between oncogenic events and microenvironmental processes in breast cancer." (PMID 24598028, 2014). "We discovered that TNF-α, when combined with WA or Cel, effectively sensitized breast cancer MDA-MB-231 cells to TNF-α-mediated induction of apoptosis by targeting its effector signaling pathway, i.e. NF-κB." (PMID 25419573, 2014).
breast carcinoma (continued). "We found a highly significant correlation between PR/ER expression and TNF-α/ NF-κB level in breast cancer." (PMID 24864130, 2014). "In the current case-control study, we determined the associations between potentially functional SNPs in the TNF-α, TNFRSF1A and TNFRSF1B genes and breast cancer susceptibility." (PMID 25010932, 2014). "For post-menopausal women, significant associations with breast cancer risk were observed for NFKB1 ins/del and del/del genotypes, IL-8 TT genotype, IL-10 TT genotype, TNF c.-418 GA and AA genotypes, and TNF c.-488 GA genotype." (PMID 25559835, 2014). "It has been reported that normal serum TNF-α levels are in the pg/ml range but they are approximately 20–25% higher in breast cancer tissue as compared to normal tissue." (PMID 25419573, 2014). "In accordance with this evidence, our results suggest that TNF-α sensitizes human breast cancer cells, MDA-MB-231 to low doses of WA and Cel, leading to apoptosis due to suppression of the NF-κB signaling pathway." (PMID 25419573, 2014). "In vivo murine breast models suggest increased expression and activity of TNFα results in many cancer-promoting functions and that inhibition of TNFα expression leads to reduced breast cancer malignancy." (PMID 25566498, 2014). "In HCT116 cells, a colon cancer cell line, TNFα has been shown to inhibit proliferation and induce apoptosis while in the breast cancer cell line T47D both inhibition and stimulation of proliferation has been seen." (PMID 24296981, 2014). "The expressions of NF-κB and TNF-α were significantly and strongly correlated with tumor size, tumor stage, and lymph node metastasis in breast cancer tissue (P < 0.05, resp)." (PMID 24864130, 2014). "While there are numerous studies of either TNFα or vitamin D in breast cancer, studies on their interactions are scarce." (PMID 24473087, 2014). "BZYQ has the potential of alleviating paclitaxel chemotherapy-related fatigue in 4 T1 breast cancer mice by reducing the serum levels of TNF-α and modulating the level of MDA and the SOD activity." (PMID 25511260, 2014). "For pre-menopausal women, significant associations with breast cancer risk were observed for NFKB1 ins/del and del/del genotypes, NFKBIA CT genotype, IL-8 TT genotype, IL-10 TT genotype, and TNF c.-418 GA and AA genotypes." (PMID 25559835, 2014). "In normal breast tissue, TNF-α regulates cell proliferation through its pro-apoptotic effects, but in breast cancer, the inhibition of the apoptotic pathway and the enhancement of the survival and proliferation effects contribute to tumor cell proliferation." (PMID 25010932, 2014). "This was evident by stimulation of breast cancer cells with TNF-α, which promoted re-localization and accumulation of NLK in the cytoplasm." (PMID 24816797, 2014). "Prolonged exposure of human breast cancer MCF-7 cells to tumor necrosis factor-α (TNF-α) induces the expression of HOTAIR and EMT." (PMID 25491133, 2014). "Based on the essential requirement for an inflammatory microenvironment in tumor formation, we investigated the effects of TNF-α on apoptosis in vitro in breast cancer MDA-MB-231 cells when combined with natural products with proteasome-inhibitory activities." (PMID 25419573, 2014). "Together, these results suggest that TNFα regulates PTX3 expression in bone metastatic breast cancer cells at both mRNA and protein levels." (PMID 24457902, 2014). "In the present study, we attempt to investigate the expression of PR, ER, NF-κB, and TNF-α in human breast cancer and the possible correlations of these four biomarkers with clinicopathological features such as tumor grade, stage, and metastasis." (PMID 24864130, 2014).
breast carcinoma (continued). "When 25OHD and cytokines/ratios were combined in our analyses, synergistic associations on ER status were found between 25OHD and TNFα and IL5, as well as several cytokine ratios, in premenopausal breast cancer patients." (PMID 24473087, 2014). "In conclusion, PR and ER are highly expressed, with significant correlation with tumor grade, TNM stage, and lymph node metastasis as well as with TNF-α and NF-κB expression in breast cancer." (PMID 24864130, 2014). "PTX3 expression was also up-regulated in a bone metastatic breast cancer cell line and further enhanced by pro-inflammatory cytokine TNFα." (PMID 24457902, 2014). "The DAC effect was evaluated in breast cancer (BC) cell lines by gene expression analysis: at the used concentrations, there is a role appearing for treatment in different cellular processes linked to TNF-α-dependent apoptosis." (PMID 25077705, 2014). "We demonstrated that the expression of adipogenesis-related genes HOXC8, HOXC9, FABP4 and HSL in adipose tissue adjacent to malignant breast tumors was down-regulated and the level of inflammatory cytokines, like TNFα and MCP-1, was up-regulated." (PMID 25291184, 2014). "In this study, we demonstrate that KSG-002, a novel herbal formula, suppresses highly metastatic breast cancer cells by inhibiting NF-κB-mediated TNFα production from TAMs." (PMID 23818931, 2013). "Downregulation of endogenous hPEBP4 in breast cancer cells sensitized cells to TNF-α-induced apoptosis and cell cycle arrest." (PMID 23451095, 2013). "The present findings, therefore, confirm that inflammatory markers, specifically CRP and TNF-α are elevated in newly diagnosed patients with breast cancer." (PMID 23374911, 2013). "Using a BALB/c breast cancer model, we found that etodolac significantly reduced lung metastasis, possibly due to macrophages expressing increased IA/IE and TNFα, but decreased M2 macrophage-related genes expressions (Ym1, TGFβ)." (PMID 23667623, 2013). "For example, NF-κB-mediated up-regulation of Twist is required for TNFα-induced EMT of breast cancer." (PMID 23431386, 2013). "Our findings pinpoint the devastating TNFα activities to be the life-threatening stage of metastasis formation, and these findings have a profound importance for breast cancer therapy." (PMID 24369447, 2013). "Our results indicate that plasma, IL-6, and TNF-α promote breast cancer cell growth as aggregates and induce adhesive recruitment of BCa cells on E-selectin coated surfaces under flow." (PMID 23372803, 2013). "These dramatic findings indicate that TNFα can turn into a strong prometastatic factor, suggesting a paradigm shift in which clinically approved inhibitors of TNFα would be applied in breast cancer therapy." (PMID 24369447, 2013). "Under obese condition, adipose tissue becomes “inflamed” to produce excess amount of inflammatory adipokines, such as tumor necrosis factor alpha (TNFα), leptin and lipocalin-2, which promote breast cancer cell survival, proliferation and tumor development." (PMID 24113220, 2013). "TGFβ is a potent MS growth factor and synergizes with TNFα to induce stem cell features in breast cancer cells." (PMID 23372804, 2013). "Breast cancer cells exposed to TGF-β and TNF-α lead to the generation of breast cancer cells with stem-like characteristics by induction of EMT." (PMID 24179490, 2013). "It was also reported that the extract of huanglian, a medicinal herb, induced cell growth arrest and apoptosis by upregulation of IFN-β and TNF-α in human breast cancer cells." (PMID 24379889, 2013). "Human A498 renal carcinoma or MCF-7 breast carcinoma cell lines were co-cultured with the U937 monocytic-like cell line in the presence of TNFα (1 ng/ml)." (PMID 23874303, 2013). "Taken together, we conclude that KSG-002 suppresses breast cancer growth and metastasis through targeting NF-κB-mediated TNFα production in macrophages." (PMID 23818931, 2013).
breast carcinoma (continued). "We recently reported anti-oxidant property of chloroform fraction of Centratherum anthelminticum (L.)seeds (CACF) by inhibiting tumor necrosis factor-α (TNF-α)-induced growth of human breast cancer cells." (PMID 23437193, 2013). "In this study, we demonstrate that a new herbal formula, KSG-002, suppresses breast cancer growth and metastasis by blocking NF-κB-dependent TNFα production from macrophages." (PMID 23818931, 2013). "In this study, we demonstrate that costunolide suppresses tumor growth and metastases of MDA-MB-231 highly metastatic human breast cancer cells via inhibiting TNFα-induced NF-κB activation." (PMID 23997800, 2013). "Ultimately these effects promote apoptosis induction, which in ER+ breast cancer cells is mediated by autocrine TNFα production." (PMID 24403234, 2013). "Positive cross-talk between 17β-estradiol and TNFα in inflammatory and angiogenic pathways, and the ability of TNFα to modulate gene regulation by 17β-estradiol may explain, in part, why associations were strongest for premenopausal EA women and ER positive breast cancers." (PMID 23991131, 2013). "In this study, we found that Saussurea lappa Clarke-derived costunolide suppressed TNFα-induced MDA-MB-231 breast cancer cell migration and invasion by inhibiting NF-κB activity." (PMID 23997800, 2013). "Studies have also found that ulinastatin enhances the inhibitory effect of docetaxel in breast cancer by a mechanism consistent with the down-regulated expression of IL-6, IL-8, and TNF-α." (PMID 23575450, 2013). "Antibodies, either alone or in combination with TNF-α, were tested for their effects on breast cancer cell proliferation." (PMID 23033967, 2012). "While total expression of LPL did not correlate with staging of breast cancer, the phosphorylation of LPL enabled breast cancer cell line resistance to TNF-α." (PMID 22194750, 2012). "Several studies have suggested that TNF-α plays an important role in the molecular events that link inflammation with development and evolution towards breast cancer." (PMID 23263670, 2012). "For instance, tumor necrosis factor α (TNFα) induces HER2 phosphorylation in breast cancer cells via c-Src activation." (PMID 22482061, 2012). "It was recently shown that TNFα secretion from cultured macrophages was significantly increased after incubation with breast cancer tumor supernatants, and resulted in enhanced tumor cell invasion and adherence to endothelium." (PMID 22731827, 2012). "Recently, the new finding that TNF-α induces EMT in MCF-7 breast cancer cells reinforced the connection between inflammation and EMT." (PMID 22938142, 2012). "Such concentrations are clearly in the range of plasma levels of docetaxel in breast cancer patients after docetaxel infusion (10 to 75 nM) and are likely sufficiently high to induce TNF expression in even poorly vascularized tumors." (PMID 22225778, 2012). "It remarkably sensitizes breast cancer cells to tumor necrosis factor (TNF)-related apoptosis-inducing ligand-mediated apoptosis." (PMID 22988474, 2012). "By Electrophoretic Mobility Shift Assay (EMSA) using specific κB probe, we found sustained nuclear NF-κB activity in MCF7 and BT-474 and to a minor extent in MDA-MB-231 breast cancer cells compared to MCF10A cells after TNFα treatment." (PMID 22675457, 2012). "The results described here indicate that the direct target of TNF-α in the Hs578T breast cancer cell line increases the levels of certain pro-apoptotic factors that modulate different cellular networks that direct the cells towards death." (PMID 23263670, 2012). "In a breast cancer xenograft model, locally injected human TNF resulted in growth inhibition of established tumours." (PMID 23905066, 2012). "Among the factors secreted by macrophages, IL-6 and TNF-α have important implications for breast cancer." (PMID 22529912, 2012).